TMEM143 (transmembrane protein 143)
Synonyms: FLJ10922
Tractability: Antibody: UniProt predicts a signal peptide or a membrane-spanning region. PROTAC: its protein half-life has been measured.
Gene: Protein-coding gene on chromosome 19 (48,332,355 to 48,364,245, reverse strand). Ensembl gene ENSG00000161558.
Subcellular location: Membrane
Subcellular location (Human Protein Atlas): Nucleoli fibrillar center
Gene Ontology:
Molecular function: protein binding
Cellular component: mitochondrion; membrane
Genetic constraint (gnomAD): Loss-of-function variants: 43 observed, 37.5 expected, observed/expected ratio (o/e) 1.15, 90% interval 0.9 to 1.48. The upper end of that interval is the gene's LOEUF score, 1.48, which puts it in group 6 of 6, group 1 being the genes least tolerant of losing a copy. Missense variants: 592 observed, 572.82 expected, observed/expected ratio (o/e) 1.03, 90% interval 0.96 to 1.11. Synonymous variants: 286 observed, 261.86 expected, observed/expected ratio (o/e) 1.09, 90% interval 0.99 to 1.21.
Homologues: Orthologues: chimpanzee TMEM143 (99% identical), macaque TMEM143 (97% identical), rabbit TMEM143 (90% identical), guinea pig TMEM143 (88% identical), pig TMEM143 (88% identical), dog TMEM143 (84% identical), mouse Tmem143 (84% identical), rat Tmem143 (84% identical), tropical clawed frog tmem143 (50% identical). Paralogues in human: PROSER2 (12% identical).
Diseases named in the same sentence as TMEM143 in open-access papers:
TMEM143 is named in the same sentence as 3 diseases in open-access papers, as found by Europe PMC text mining. Sharing a sentence is not in itself a finding about the gene and the disease. The quoted sentences say what the papers report.
lung carcinoma (1 paper, 2021). "Transmembrane protein 143 was present at different levels in different stages of lung cancer and may be important in the early diagnosis and prognosis of cancer." (PMID 33728331, 2021). "The levels of transmembrane protein 143, cadherin 5, fibronectin 1, and collectin-11 decreased significantly in the serum of patients with metastases compared with those of nonmetastatic lung cancer patients." (PMID 33728331, 2021).
TMEM143 also shares sentences with these, for which no sentence is quoted: asthma (1 paper); cancer (1).